SNAP25 (synaptosome associated protein 25)
Diseases named in the same sentence as SNAP25 in open-access papers (continued):
Sharing a sentence is not in itself a finding about the gene and the disease.
infection (11 papers, 2009 to 2025). The state of being infected such as from the introduction of a foreign agent such as serum, vaccine, antigenic substance or organism. "Lastly, the data show that the infection and consequent inflammation were associated with reduced expression of genes linked to the development and maturation of the central nervous system including Pvalb, calb and Snap25." (PMID 40059770, 2025). "In the infection group, the location of nerve fibers expressing SNAP-25 mirrored that of the control group." (PMID 38956647, 2024). "Intriguingly, when the infection had proceeded for 6 h, the size of the SNAP25‐CVs was significantly smaller in cells infected with the wild‐type strain than that found in cells infected with the ∆sseK1/2/3 mutant." (PMID 38817622, 2023). "In great contrast, lentiPirtLCA at 0.2 × 104 TU dose did not induce any cleavage of SNAP-25 in cultured spinal cord neurons (SCNs) whereas higher dose of virus at 5.4 × 104 TU only produced negligible cleavage of SNAP-25 even at day 5 after infection." (PMID 34445536, 2021). "Next, we checked the time course of appearance of SNAP-25 cleavage in mDRGs and mTGNs following infection by lentiPirtLCA." (PMID 34445536, 2021). "We found that, CRMP2, Septin 5 and SNAP25 genes were significantly up regulated in chicken brain in the time of infection." (PMID 22361110, 2012). "The extent of SNAP-25 cleavage is related to the infection dose." (PMID 34445536, 2021). "In addition, immunofluorescence staining and western blot provided the evidence that Snap25 expression decreased through the infection of primary hippocampal neurons with miR-210-5p mimic when compared with the control group, whereas miR-210-5p inhibitor increased the expression of Snap25." (PMID 30483048, 2018). "We found that SseK3 catalyzes Arg‐GlcNAcylation on SNAP25 and promotes SIF biogenesis mediated by the SseK3–SNARE axis and that infection by S. Typhimurium induces the expression of TRIM32, which antagonizes the activity of SseK3 by ubiquitination‐mediated degradation." (PMID 38817622, 2023). "Following infection of primary cultures of rat embryonic DRG neurons, the different BoNT LC induced efficient cleavage of their corresponding target Soluble N-ethylmaleimide-sensitive-factor Attachment protein Receptor (SNARE) protein (VAMP, SNAP25, syntaxin)." (PMID 30791373, 2019). "At 24 h post-infection (pi) the neuronal cultures were processed for Western blotting using antibodies specific for GFP and antibodies that recognize both the native (about 25 kDa) and the cleaved (about 24 kDa) forms of SNAP25." (PMID 30791373, 2019). "Importantly, this figure also shows that infection with GFP-BoNT-A LC and BoNT-A LC vectors induced a dose-dependent cleavage of SNAP25, demonstrating that both proteins are functional." (PMID 30791373, 2019). "Not surprisingly, the cleavage of SNAP-25 is infection dose dependent." (PMID 34445536, 2021). "We used this antibody in these tests because in the case of organotypic DRG cultures most cells would escape infection (only the outgrowing neurites could be infected) and the presence of large amounts of noncleaved SNAP25 from noninfected cells could mask the results." (PMID 30791373, 2019).
neurodevelopmental disorder (4 papers, 2017 to 2025). A behavioral and cognitive disorder with onset during the developmental period that involves impaired or aberrant development of intellectual, motor, or social functions. "Also, altered Snap25 (synaptic vesicle exocytosis protein) expression is associated with seizures and neurodevelopmental disorders." (PMID 41301530, 2025). "SNAP25 gene polymorphisms are associated with ADHD, another neurodevelopmental disorder." (PMID 28878621, 2017).
kidney (2 papers, 2012 to 2022). "We performed qRT-PCR analyses to investigate mRNA expression of gustducin, TrpM5, NeuroD, SNAP25, and polycystic kidney disease 2-like 1 (PKD2L1)." (PMID 22536412, 2012).
movement disorder (2 papers, 2021 to 2022). Neurological conditions resulting in abnormal voluntary or involuntary movement, which may impact the speed, fluency, quality and ease of movement. "Given its fundamental role in nervous transmission, de novo SNAP25 variants are associated with various neurological disorders, such as epilepsy, movement disorders, and psychiatric conditions." (PMID 35350397, 2022). "Usually, patients with SNAP25-DEEs show seizure's onset after 2 years of age, with generalized seizures and a frequent association to movement disorders, while NAPB-associated DEEs are characterized by a high frequency of clonic seizures and an evolution in multifocal epileptic encephalopathy." (PMID 35350397, 2022).
neuromuscular disease (1 paper, 2024). "Regarding neuromuscular diseases, the biological significance of SNAP25 cleavage in the spinal cord ventral horn after muscular administration is uncertain." (PMID 38787077, 2024).
vascular disorder (1 paper, 2022). A general term used to describe any disease affecting blood vessels]. "Increased CSF levels of PSD-95, SNAP-25, and Ng were, however, not specific for AD and were present in sporadic cases with inflammatory or vascular disorders as well." (PMID 35461266, 2022). "High CSF levels of PSD-95 and SNAP-25 were, however, not specific for AD and were present in sporadic cases with inflammatory or vascular disorders as well." (PMID 35461266, 2022).
SNAP25 also shares sentences with these, for which no sentence is quoted: metabolic syndrome (5 papers); brain diseases (4); cognitive disorder (4); adenocarcinoma (2); cerebellar ataxia (2); frontotemporal dementia (2); Parkinson's (2); primary immunodeficiency (2); 22q11.2 deletion syndrome (1); adenoma (1); ADNP syndrome (1); alcohol use disorder (1); amyotrophic lateral sclerosis (1); anxiety disorder (1); asthma (1); astrocytoma (1); autoimmune disease (1); autoimmune thyroid disease (1); basal cell carcinoma (1); bipolar I disorder (1); brain cancer (1); brain inflammation (1); chronic obstructive pulmonary disease (1); Cirrhosis (1); Cushing syndrome (1); cyst (1); cystitis (1); diverticular disease (1); Dravet syndrome (1); dyslexia (1).
A further 29 diseases each share a sentence with SNAP25 in 1 paper.